REEP4 (receptor accessory protein 4)
Description:
Microtubule-binding protein required to ensure proper cell division and nuclear envelope reassembly by sequestering the endoplasmic reticulum away from chromosomes during mitosis. Probably acts by clearing the endoplasmic reticulum membrane from metaphase chromosomes.
Synonyms: C8orf20; PP432; FLJ22246; FLJ22277; Yip2c
Tractability: Antibody: UniProt predicts a signal peptide or a membrane-spanning region. PROTAC: ubiquitination databases record sites on it; its protein half-life has been measured.
Gene: Protein-coding gene on chromosome 8 (22,138,019 to 22,141,951, reverse strand). Ensembl gene ENSG00000168476.
Subcellular location: Endoplasmic reticulum membrane
Subcellular location (Human Protein Atlas): Endoplasmic reticulum
Gene Ontology:
Molecular function: protein binding; microtubule binding
Biological process: mitotic nuclear membrane reassembly; nuclear envelope organization; endoplasmic reticulum tubular network organization
Cellular component: endoplasmic reticulum; cytoplasmic microtubule; endoplasmic reticulum membrane; endoplasmic reticulum tubular network
Genetic constraint (gnomAD): Loss-of-function variants: 17 observed, 32.44 expected, observed/expected ratio (o/e) 0.52, 90% interval 0.36 to 0.79. The upper end of that interval is the gene's LOEUF score, 0.79, which puts it in group 3 of 6, group 1 being the genes least tolerant of losing a copy. Missense variants: 340 observed, 352.55 expected, observed/expected ratio (o/e) 0.96, 90% interval 0.88 to 1.05. Synonymous variants: 157 observed, 142.1 expected, observed/expected ratio (o/e) 1.1, 90% interval 0.97 to 1.26.
Homologues: Orthologues: chimpanzee REEP4 (99% identical), macaque REEP4 (97% identical), pig REEP4 (91% identical), mouse Reep4 (88% identical), dog REEP4 (88% identical), guinea pig REEP4 (88% identical), rat Reep4 (86% identical), tropical clawed frog reep4 (64% identical), Caenorhabditis elegans T19C3.4 (35% identical), Drosophila melanogaster CG5539 (21% identical), Caenorhabditis elegans yop-1 (18% identical), Caenorhabditis elegans T03F6.6 (15% identical), and 3 more. Paralogues in human: REEP2 (53% identical), REEP3 (53% identical), REEP1 (53% identical), REEP5 (19% identical), REEP6 (19% identical).
Diseases named in the same sentence as REEP4 in open-access papers:
REEP4 is named in the same sentence as 23 diseases in open-access papers, as found by Europe PMC text mining. Sharing a sentence is not in itself a finding about the gene and the disease. The quoted sentences say what the papers report.
blepharospasm (3 papers, 2019 to 2024). "In preceding work, a deleterious REEP4 variant [GRCh38/hg38, NC_000008.11:g.22140245G>A, NM_025232.4:c.109C>T, p.Arg37Trp] was found to co-segregate with blepharospasm (BSP) in a large African-American pedigree." (PMID 39262575, 2024). "REEP4 mutations were associated with neurological disorders such as Meige syndrome and blepharospasm." (PMID 37818043, 2023). "Interestingly, a recent study showed that deleterious variants in CACNA1A, REEP4, TOR2A, ATP2A3, HS1BP3, GNA14, and DNAH17 were involved in blepharospasm, and none of these variants except for CACNA1A has been reported to be associated with blepharospasm." (PMID 32038460, 2019).
Dystonia (1 paper, 2024). An abnormally increased muscular tone that causes fixed abnormal postures. "The causal contributions of REEP4 variants to dystonia and other neurological disorders remains indecisive." (PMID 39262575, 2024). "In silico analysis identified numerous deleterious REEP4 variants in published screening studies of dystonia and several highly deleterious single nucleotide REEP4 variants in ClinVar." (PMID 39262575, 2024). "Without comprehensive co-segregation analyses in pedigrees with dystonia and trio analyses in early-onset neurological disorders, it is not possible to convincingly ascribe pathogenicity to published and reported REEP4 variants." (PMID 39262575, 2024). "Sanger sequencing was used to screen subjects (N = 307) with BSP and BSP-plus dystonia affecting additional anatomical segments (BSP+) phenotypes for variants in REEP4." (PMID 39262575, 2024). "Follow-up screenings of large cohorts of patients with BSP and other forms of dystonia for REEP4 variants is a logical and necessary next step in the study of BSP." (PMID 39262575, 2024). "Other REEP4 variants have been reported in genetic screening studies of dystonia." (PMID 39262575, 2024). "In aggregate, existing genetic, cellular, and clinical data suggest that REEP4 is a candidate gene for dystonia and other neurological disorders." (PMID 39262575, 2024). "In conclusion, more work is required to establish a convincing role for REEP4 in dystonia and other neurological disorders." (PMID 39262575, 2024).
focal dystonia (1 paper, 2024). A dystonia that is localized to a specific part of the body. "It is possible that REEP4 plays a more important role in other forms of focal dystonia or spastic paraplegia." (PMID 39262575, 2024).
glioma (1 paper, 2024). A benign or malignant brain and spinal cord tumor that arises from glial cells (astrocytes, oligodendrocytes, ependymal cells). "To explore whether REEP4 is indeed involved in the pathological process of glioma, we chose lower-grade glioma (LGG) as the object of study due to its great heterogeneity with GBM." (PMID 38552216, 2024). "Therefore, we speculate that REEP4 may participate in the pathological evolution of gliomas and play an important regulatory role." (PMID 38552216, 2024).
hereditary spastic paraplegia 31 (1 paper, 2012). A rare type of hereditary spastic paraplegia usually characterized by a pure phenotype of proximal weakness of the lower extremities with spastic gait and brisk reflexes, with a bimodal age of onset of either childhood or adulthood (>30 years). "The six REEP proteins include REEP1, which is mutated in hereditary spastic paraplegia 31 (one of a group of disorders characterized by progressive weakness and stiffness of the legs), and REEP4, loss of which causes paralysis in Xenopus." (PMID 22870394, 2012). "Mutation of REEP1 causes hereditary spastic paraplegia 31 in humans, which is characterized by progressive weakness and stiffness of the legs, and mutation of REEP4 causes lower body paralysis in an animal model." (PMID 22870394, 2012).
pancreatic cancer (1 paper, 2023). "A study found that in pancreatic cancer, high expression of REEP4 was associated with tumor invasion and poor prognosis." (PMID 37818043, 2023).
renal carcinoma (1 paper, 2024). A carcinoma arising from the epithelium of the renal parenchyma or the renal pelvis. "Subsequently, we conducted in vitro experiments to confirm the overexpression of REEP4 in KIRC tumor tissues and renal cancer cells." (PMID 38947393, 2024).
Spastic paraplegia (1 paper, 2024). Complete loss of the ability to move the lower limbs accompanied by spasticity of the lower limbs. "The REEP4 paralogs, REEP1 and REEP2, are associated with spastic paraplegia." (PMID 39262575, 2024).
cancer (4 papers, 2018 to 2024). A tumor composed of atypical neoplastic, often pleomorphic cells that invade other tissues. "The results suggest that the cellular signaling pathway regulated by REEP4 is involved in the proliferation, differentiation, and immune microenvironment of cancers." (PMID 38552216, 2024). "Although The REEP family has been investigated in cancer development, the specific relationship between REEP4 and cancer remains unclear." (PMID 38947393, 2024). "In addition, we found that REEP4 was primarily enriched in cancer-related cell signal pathways such as the cell cycle, MAPK signaling pathway, HIF-1 signaling pathway, NOD-like receptor signaling pathway, TNF signaling pathway, etc., through KEGG signal pathway analysis." (PMID 38552216, 2024). "Therefore, using the TIMER database, we first found that REEP4 was negatively correlated with the purification of cancer cells and exhibited a high positive correlation with the degree of infiltration of five different immune cells (B cell, CD4+ T cell, macrophage, neutrophil, and dendritic cell)." (PMID 38552216, 2024). "This confirmed that REEP3, REEP4, TEP1, and EEPD1 and their network proteins were involved in immunoregulatory functions and cancer development." (PMID 37818043, 2023). "Taking advantage of Gene Expression Profiling Interactive Analysis (GEPIA) and The Cancer Genome Atlas Program (TCGA), we compared mRNA expression of REEP3, REEP4, TEP1, and EEPD1 between GBM tumor and normal brain tissue." (PMID 37818043, 2023). "Lower grade glioma (LGG), as a malignant tumor, is accompanied by abnormalities in mitosis, but there have been no reports of REEP4 so far." (PMID 38552216, 2024). "Taken together, REEP3, REEP4, TEP1, and EEPD1 were related to many cellular functions including cell proliferation, differentiation, the pathogenesis of neurological disorders and cancer biology." (PMID 37818043, 2023). "Since REEP4 has not been reported in cancers to date, whether the abnormal high expression of REEP4 has an impact on the prognosis of LGG aroused a strong interest in this matter on our part." (PMID 38552216, 2024).
tumor (3 papers, 2023 to 2024). "In the process of biology, REEP4 participates in the process of regulating cellular mitosis, thereby affecting the proliferation of tumor cells." (PMID 38552216, 2024). "Comparing KIRC tumor tissues to normal tissues, we observed a significant upregulation in REEP4 expression, with higher levels of REEP4 correlating positively with tumor malignancy." (PMID 38947393, 2024). "More importantly, REEP4 has the potential to become a new star in the field of anti-tumor treatment." (PMID 38552216, 2024). "Based on the potential value of anti-tumor immunotherapy, this study further explored the impact of REEP4 on the LGG immune microenvironment." (PMID 38552216, 2024). "More importantly, it systematically revealed the regulatory relationship between REEP4 and immune cell infiltration level in tumor microenvironment, especially M2 tumor related macrophages and the exploration of the potential value of anti-tumor immunotherapy." (PMID 38552216, 2024). "Therefore, revealing the relationship between REEP4 and immune checkpoints will help to improve the progress of anti-tumor immunotherapy." (PMID 38552216, 2024). "In addition, the impact of REEP4 on the tumor immune microenvironment and the potential value of anti-tumor immunotherapy were revealed for the first time, broadening the understanding of molecular biology of REEP4." (PMID 38552216, 2024). "Subsequently, we considered whether REEP4 has become a target of anti-tumor immunotherapy." (PMID 38552216, 2024). "As shown in, the REEP3, REEP4, TEP1, and EEPD1 had significantly higher expression in GBM tumor tissues compared to normal tissues." (PMID 37818043, 2023). "To evaluate REEP3, REEP4, TEP1 and EEPD1 mRNA levels in multiple tumor and normal samples, we downloaded and compiled data from 11124 samples (Tumor =7260, Normal =3864) from the TCGA database." (PMID 37818043, 2023). "The GEPIA and TCGA datasets were used to analyze the expression patterns of REEP3, REEP4, TEP1, and EEPD1 in tumor tissue and normal tissue." (PMID 37818043, 2023). "The result showed that the expression of REEP3, REEP4, TEP1, and EEPD1 was significantly higher in GBM tumor tissue." (PMID 37818043, 2023). "REEP3, REEP4, TEP1 and EEPD1 was differentially expressed in 14, 17, 14, 13 tumor types, respectively." (PMID 37818043, 2023). "This can be used as a highly sensitive biological target for diagnosing and treating LGG, and makes up for the lack of focus on REEP4 in the study of tumor pathogenesis." (PMID 38552216, 2024). "REEP4 was upregulated in all 17 types of tumor as compared to normal tissue while the expression level of the rest of the efforts is tumor-specific." (PMID 37818043, 2023).
metabolic disease (1 paper, 2023). A congenital disorder (due to inherited enzyme abnormality) or acquired (due to failure of a metabolically important organ) disorder resulting from an abnormal metabolic process. "REEP4 displays direct phosphorylation-dependent interactions with 14-3-3, which regulates various tumors, metabolic diseases and neurodegenerative diseases." (PMID 37238941, 2023).
REEP4 also shares sentences with these, for which no sentence is quoted: neurological disorders (2 papers); Anosmia (1); COVID-19 (1); hepatocellular carcinoma (1); hereditary spastic paraplegia (1); Kidney Clear Cell Carcinoma (1); major depression disorder (1); Martsolf syndrome (1); melanoma (1); myelodysplastic syndrome (1); myopathy (1); neurodegenerative disease (1).